TNF (tumor necrosis factor)
Diseases named in the same sentence as TNF in open-access papers (continued):
Sharing a sentence is not in itself a finding about the gene and the disease.
Obesity (continued). "However, we focused that obesity results in a chronic low-grade inflammatory state, with increased pro-inflammatory cytokines, TNF-α and IL-6, causing the activation of stress-induced MAPK signaling." (PMID 34064531, 2021). "Interestingly, human population studies indicated an association of gain-of-function TNF −304G/A polymorphism with obesity-related airway hyperresponsiveness in asthmatics." (PMID 34573120, 2021). "In addition to altered levels of leptin and adiponectin, increased levels of obesity-related adipokines such as interleukin-6 (IL-6), interleukin-8 (IL-8), tumor necrosis factor-α (TNF-α), visfatin and resistin are associated with increased cancer risk." (PMID 33987528, 2021). "Obesity, a key component of metabolic syndrome, causes adipose tissue remodeling and induces increased secretion of pro-inflammatory adipokines, including TNF-α and IL-6, and decreased anti-inflammatory adipokines like adiponectin, which potentially accelerates hepatocarcinogenesis." (PMID 33427937, 2021). "Thus, obesity is directly associated with low-grade chronic inflammation, as the expression of proinflammatory cytokines (IL-6, IL-8, PCR, and TNF-α) is shown to be increased in this pathology." (PMID 33716759, 2021). "Obesity was associated with worse disease activity and disease management in both PsA and RA and a detrimental response to anti-tumor necrosis factor alpha (anti-TNF) treatments." (PMID 34300360, 2021). "Notably, increased HAT activity and therefore, hyperacetylation of H3K9/14 at the promotor site of TNF-α, was shown to be associated with liver inflammation, leading to fibrosis in obesity-induced mice." (PMID 33868227, 2021). "In agreement, the lower promoter methylation profiles found in obese subjects were associated with higher pro-inflammatory cytokines IL-6 and TNF-α plasma levels that play crucial roles in an obesity-associated increased risk of diabetes and cardiovascular diseases." (PMID 34869683, 2021). "However, both detrimental and protective effects of TNF in obesity-associated metabolic disease and adipose tissue homeostasis are reported." (PMID 34099626, 2021). "CLS agglomerates, in turn, might play a significant role not only in the secretion of IFN-γ and TNF-α as a result of Th1 cell activity, but also in the obesity-associated systemic inflammation present before the surgery." (PMID 34108550, 2021). "TNFα-mediated inflammation, obesity, and insulin resistance are associated with T2DM73." (PMID 34675276, 2021). "In obesity, the increase in leptin levels is associated with the state of leptin resistance, in addition to the increase in reactive oxygen species (ROS), IL-6, TNF-α, and chemokines." (PMID 33807959, 2021). "The mechanistic pathway implicated in obesity‐related hypercoagulability includes the actions of adipocytokines, coagulation factors hyperactivity and increased inflammation (tumour necrosis factor [TNF], interleukin‐6 [IL‐6]) among others." (PMID 32904932, 2021). "TNFα, which is associated with obesity, has been linked to the onset of IR and T2DM." (PMID 35052752, 2021). "Circulating serum levels of adiponectin are decreased in patients with obesity, type 2 diabetes, metabolic syndrome, or cardiovascular disease inflammation, and are associated with an increased release of pro-inflammatory cytokines like IL-6 and TNF-α." (PMID 33418879, 2021). "Since elevated levels of free PA and TNFα have been reported in obesity, their cross-talk may be a key driver of obesity-associated chronic inflammation via excessive chemokine production." (PMID 34359908, 2021). "In some studies, obesity was related to frequent perianal complications of CD and high rates of relapses and hospitalization as well as short time to loss of response to anti-tumor necrosis factor (TNF) agents." (PMID 34381741, 2021). "TNF-α plays a central role in the state of insulin resistance associated with obesity." (PMID 34003397, 2021).
Obesity (continued). "It has been known that both diabetes and obesity cause a low grade pro-inflammatory state in the body with increased secretion of cytokines including interleukin (IL)-1, IL-6, IL-8 and tumor necrosis factor-α (TNF-α)." (PMID 34690930, 2021). "In our study, obesity-induced damage to the female reproductive system is associated with increases in IL-6 and TNF-α mRNA and protein expression levels based on an agreement in the results of IHC staining, Western blotting and quantitative RT-PCR in the HFD female reproductive organs." (PMID 34560886, 2021). "Additionally, TNFα assumes a major role in the development of muscle insulin resistance in both obesity and metabolic syndrome, as well as in healthy individuals with insulin resistance in skeletal muscle caused by TNFα treatment." (PMID 34281257, 2021). "TNF-α plays a critical role in several autoimmune diseases, such as rheumatoid arthritis, and may mediate obesity-linked insulin resistance in type 2 diabetes." (PMID 35052401, 2021). "Although the molecular mechanisms underlying the regulatory effects of TNFα in adipocytes and adipose tissue during obesity are well-studied, there is little information about the molecular consequences of hepatocytes in response to TNFα exposure, despite its upregulation in obesity." (PMID 34576943, 2021). "Taken together, the findings of the network pharmacology approach suggest that the combined mechanism of CR against obesity may reduce inflammation by modulating macrophages and their associated TNF and chemokine signaling pathways." (PMID 34360840, 2021). "In contrast, the poor response seen in Cluster E may be explained by its highest observed BMI levels and possible systemic inflammation from increased levels of several obesity-associated cytokines (TNF-α, IL-6, and leptin)." (PMID 33705484, 2021). "Previous studies have shown that different inflammation biomarkers, such as CRP, TNFα and IL-6, were differently associated with body composition and these may further differ by obesity level and sex." (PMID 33557067, 2021). "Obesity is strongly associated with chronic inflammatory processes and when examining inflammation-related genes such as IL-1β as well as TNF-α we found a significantly attenuated expression in liver tissue of transgenic miR-100 mice that underwent a HFD for 16 weeks." (PMID 34488621, 2021). "In obesity settings, monocytes exhibit an inflammatory phenotype associated with the increased expression of CD11b, CD11c and HLA-DR surface markers, along with higher secretion of proinflammatory cytokines/chemokines such as TNF-α, IL-6, IL-1β, and MCP-18,10." (PMID 33859296, 2021). "Furthermore, EA ameliorated obesity-associated inflammatory responses through decreasing area neutrophil+, area CD11b+, area F4/80+, F4/80 mRNA, TNF-α mRNA, MCP-1 mRNA, CD68 mRNA, and IL-6 mRNA in adipose tissues." (PMID 35095910, 2021). "TNF-α is one of the most extensively studied pro-inflammatory cytokines, which shows a prominent link to the onset of metabolic disorders via inducing the obesity-associated HIF-1α and low-grade chronic inflammation of the adipose tissue." (PMID 32752112, 2020). "TNF-α is associated with concurrent obesity and T2DM and correlates with HbA1c." (PMID 32089876, 2020). "In addition, RPA can reduce the serum TG, malondialdehyde, leptin and TNF-α levels caused by ovariectomies, so as to improve the lipid metabolism disorder and inhibit obesity." (PMID 32489401, 2020). "Furthermore, obesity is linked to decreased bone formation and increased bone resorption through TNF-α-induced upregulation of osteocyte-derived sclerostin and RANKL." (PMID 32708317, 2020). "Another study showed that obesity-induced TNF-α release may potentiate FM-associated pain in mouse models." (PMID 32704114, 2020). "Obesity is also associated with the production of several adipocytokines hypothesized to promote oncogenesis, including leptin, tumor necrosis factor-alpha (TNFα), interleukin-6 (IL-6), IL-7, and IL-8." (PMID 33105727, 2020).
Obesity (continued). "Indeed, obesity is associated with increased production of pro-inflammatory cytokines, such as interleukin-6 (IL-6) and tumor necrosis factor α (TNFα), leading to a chronic inflammatory state." (PMID 33266209, 2020). "Furthermore, obesity is associated with high levels of inflammatory cytokines, such as leptin, IL-6, and TNF-α, produced by adipocytes and immune cells infiltrating adipose tissue." (PMID 33343662, 2020). "In accordance with this, it has been suggested that the response of inflammatory cells to catecholamines could stimulate the production of inflammatory mediators (including TNF-α) in inflammatory pathologies such as obesity and obesity-associated diabetes." (PMID 33266248, 2020). "As expected, obesity caused a low-grade chronic inflammation, which was reflected by increased mRNA levels of the pro-inflammatory cytokines tumor necrosis factor α (Tnf-α), interleukin 1β (Il-1β) and of the macrophage marker F4/80 induced by the high-fat diet feeding." (PMID 32784488, 2020). "Furthermore, findings in humans show that maternal obesity associates with heightened uNK degranulation, as assessed by surface CD107a expression and increased production of TNF-α, corroborating this association between obesity and uNK activity." (PMID 32471078, 2020). "From a pharmacological point of view, the intestinal lipase inhibitor orlistat is of particular interest, which helps in weight reduction by decreasing levels of tumor necrosis factor alpha and interleukin 6 and may reduce the risk of obesity and CVD." (PMID 32825823, 2020). "We found that high TNF-α levels were associated with the risk of obesity." (PMID 33299020, 2020). "Indeed, obesity predisposes to a pro‐inflammatory state via increased inflammatory mediators, such as TNF‐α and IL‐6, which stimulate the liver to synthesize and secrete C‐reactive protein." (PMID 33053604, 2020). "Further, investigations assessing the impact of anti-TNF agents on intermediary metabolism seemed to show that a TNF-alpha blockade may improve insulin resistance and lipid profiles, which in turn appeared to be associated with overweight and obesity." (PMID 32545460, 2020). "Among several inflammatory signaling pathways associated with obesity induced insulin resistance, TNFα signaling was induced by tumor necrosis factor-α receptor-associated factor 2 (TRAF2), activating JNK and IKK, which contributed to the development of insulin resistance." (PMID 33208918, 2020). "Inhibiting TNF-α antagonizes the adverse effects caused by obesity." (PMID 32752112, 2020). "Interestingly, obesity-associated cytokines like IL-6 and TNF-α are able to influence many signaling pathways and induce defects in the ciliogenesis of ASCs." (PMID 32806722, 2020). "Therefore, high TNFα and IL-6 levels are also associated with MetS risk factors such as obesity, insulin resistance, and T2DM." (PMID 32178436, 2020). "As a result of chemokine production by neutrophils, macrophages are recruited into the adipose tissues where they secrete cytokines, such as tumor necrosis factor alpha (TNF-α) and interleukin-1 beta, causing obesity-mediated inflammation and impaired insulin signaling." (PMID 32277104, 2020). "The study further shows that the effects of diet on TNF-α/IL-10 ratios were linked to distinct patterns of NF-κB accumulation in the nucleus: while RelA was the NF-κB subunit most impacted by obesity in adipose tissue macrophages, cRel was the subunit affected in peritoneal macrophages." (PMID 31316525, 2019). "An excess of pro-inflammatory adipokines (leptin, TNF-α, IL-6, etc.)may be responsible for the association between asthma and obesity." (PMID 31842862, 2019). "Furthermore, increased TNF-α was associated with insulin resistance in a broad range of conditions including aging, sepsis and obesity." (PMID 31591391, 2019). "Moreover, the low-grade inflammation associated with obesity causes the infiltration of TNFα into adipocytes." (PMID 31752434, 2019).
Obesity (continued). "Dietary and plasma carboxymethyl lysine (dCML, pCML) and plasma tumor necrosis factor-α (pTNF-α) may be associated with obesity in affluent society." (PMID 31847322, 2019). "In obesity and/or T2D, a typical proinflammatory M1 polarization in the adipose tissue is observed which is associated with certain morbid factors such as increased levels of TNF-α, fatty acids, glucose, insulin, and obesity-induced hypoxia." (PMID 31718015, 2019). "Obesity in cats, similar to other species, has been associated with decreased adipose tissue mRNA expression and circulating concentrations of adiponectin as well as increased adipose tissue expression of TNFα and IL6." (PMID 31492181, 2019). "We found a reduction of a number of inflammatory cytokines in adipocytes and visceral adipose depots upon different pro-inflammatory conditions such as hypoxia, cellular hypertrophy, diet-induced obesity in association with the down-regulation of TNF-α inflammatory signaling pathway." (PMID 31453381, 2019). "Last, we could not measure other obesity-associated adipokines such as other obesity-associated adipocytokines such as TNFα, leptin, IL6, IL8, MCP1, and FABP4 because of the limited quantity of samples." (PMID 32117043, 2019). "TNF-α promotes protein degradation and may be associated with obesity-related skeletal muscle atrophy and age-related sarcopenia." (PMID 30717377, 2019). "Additionally, metabolic changes caused by obesity alter critical hematopoietic and immunologic pathways, such as TNF-α, IL-1, IL-6, and PGE2, which also have pro-tumorigenic potential." (PMID 31616626, 2019). "Obesity has also been associated with low-grade chronic inflammatory processes, and several cytokines such as tumor necrosis factor alpha (TNF-α) have been shown to be elevated in obese individuals due to an increased activity of adipose tissue-derived cytokine production and insulin resistance." (PMID 31915708, 2019). "An explanation for this association could be the fact that obesity might be considered as additional inflammation where pro-inflammatory adipokines, such as TNFα, IL1β, IL6 or MCP1, are segregated by adipose tissue and macrophages." (PMID 30786913, 2019). "Furthermore, LCN2-deficiency attenuated aging- and obesity-induced insulin resistance by inhibiting 12-lipoxygenase, an enzyme that metabolizes arachidonic acids, and tumor necrosis factor-α (TNF-α), a critical insulin resistance inducer." (PMID 31208019, 2019). "Among the factors that link obesity to carcinogenesis are the activation of the insulin/IGF-1 pathway, increased concentrations of pro-inflammatory cytokines (TNF-α, IL-1 and IL-6) and their influence on adipocytokines, and dyslipidemia, which is often associated only to obesity." (PMID 31703601, 2019). "Interestingly, the results of this meta-analysis suggested that polymorphisms in the adipokine genes, ADIPOQ, IL-1β, IL-6, and TNF-α, increase the risk of obesity." (PMID 31354816, 2019). "Moreover, IL-6 and TNFα levels have both been found to be increased in the serum of obese patients and are critical drivers of obesity-associated insulin resistance." (PMID 30787925, 2019). "Previous mechanism studies suggested that chronic inflammation contributed to the pathogenesis of obesity; the infiltration and accumulation of macrophages in adipose tissue was demonstrated to be associated with increased tumor necrosis factor-α and interleukin 6 secretion." (PMID 31767029, 2019). "We observed that increased concentrations of TNFα and IFNγ, associated with obesity and diabetes, might interfere with the anti-inflammatory effect of insulin, which in turn might promote inflammation." (PMID 31504048, 2019). "In addition, obesity has been shown to be associated with poorer response and adherence to TNF inhibitor therapy." (PMID 30635024, 2019).
Obesity (continued). "Although TNFα is elevated in diabetic patient and animal model of diabetes, little was known about its role in cellular alteration, notably regarding the Ca2+ signaling pathway and gender specificity in animal model of diabetes linked to obesity." (PMID 30792662, 2019). "Increased concentrations of tumor necrosis factor (TNF)-α and interleukin (IL)-6 associated with obesity and type 2 diabetes might interfere with the anti-inflammatory effects of insulin, which can promote inflammation." (PMID 31504048, 2019). "Furthermore, mitochondrial dysfunction caused by tumor necrosis factor-α (TNF-α), which is an inflammatory cytokine that increases in obesity, leads to smaller and condensed mitochondria and inhibits intracellular ATP synthesis in 3T3-L1 adipocytes." (PMID 31590292, 2019). "Notably, immunoregulatory IL-10, TNF-α, and IL-1 have been linked to the pathophysiology of multiple chronic disorders including pain, obesity, diabetes, metabolic syndrome, and depression/anxiety, most of which are frequently observed clinically." (PMID 31554241, 2019). "TNF-α is overexpressed in AT during obesity, and is causally linked to AT inflammation." (PMID 31766503, 2019). "Although the exact molecular mechanisms that link obesity to other MetS risk factors remains unclear, TNF-α has been shown to be associated with MetS risk factors." (PMID 30114249, 2018). "We now know that diseases that fall into the metabolic syndrome spectrum, such as T2DM and obesity, are associated with dysfunctional immunity and low low-grade inflammation, as shown by increased levels of proinflammatory cytokines such as TNF-α, IL-6, and chemotactic factors (e.g., CCL5 and CCL8)." (PMID 29765984, 2018). "This study investigated whether pulmonary fibroblasts derived from COPD versus non-COPD patients differ in their inflammatory response to dietary fatty acids (ω-6 PUFAs, ω-3 PUFAs and SFAs) and the obesity-associated cytokine TNFα in vitro." (PMID 30390648, 2018). "Increases in circulating TNF-α are associated with peripheral insulin resistance, increased plasma glucose and insulin levels before the onset of T2D, whereas the increased fasting glucose level induced by obesity can be prevented by TNF-α deficiency." (PMID 30114249, 2018). "Obesity was associated with inferior response to anti-TNF therapy across all rheumatic diseases." (PMID 29771924, 2018). "An increase in the circulating TNF-α and IL-6 concentrations is associated with increased plasma glucose, body weight and BMI, which supports the idea that inflammatory cytokines play a role in the pathogenesis of diabetes and obesity." (PMID 30914847, 2018). "C-reactive protein (CRP), an acute-phase protein secreted by the liver in response to interleukin-6 (IL-6) and tumor necrosis factor (TNF)-α, is a well-characterized marker of inflammation, and increased circulating levels have been shown to be associated with obesity and increased metabolic risk." (PMID 29760934, 2018). "A thorough evaluation of obesity as an effect modifier in clinical trials is warranted, and intentional weight loss may serve as adjunctive treatment in patients with obesity failing anti-TNF therapy." (PMID 29771924, 2018). "In our study, the TNF-α G238A SNP (rs361525) was selected based on previous studies showing positive associations between this SNP and serum levels of testosterone and insulin, obesity, and so on which all of them are the properties of PCOS." (PMID 30134857, 2018). "Obesity was associated with inferior response to anti-TNF therapy in both RCTs (20 studies; OR, 1.50 [1.24–1.80], I2 = 40%) and observational studies (34 studies; OR, 1.68 [1.48–2.00], I2 = 78%), without significant difference between subgroups (pinteraction = 0.39)." (PMID 29771924, 2018).